RBMY1D (RNA binding motif protein Y-linked family 1 member D)
Description:
RNA-binding protein which may be involved in spermatogenesis. Required for sperm development, possibly by participating in pre-mRNA splicing in the testis.
Synonyms: RBM1; RBM2; YRRM1; YRRM2; hRBMY
Tractability: No criterion of Open Targets' tractability assessment is met for any kind of drug.
Gene: Protein-coding gene on chromosome Y (21,880,076 to 21,894,526, reverse strand). Ensembl gene ENSG00000244395.
Subcellular location: Nucleus
Subcellular location (Human Protein Atlas): Nucleoplasm; Nucleoli
Gene Ontology:
Molecular function: nucleic acid binding; RNA binding
Biological process: mRNA splicing, via spliceosome
Cellular component: spliceosomal complex; nucleus
Homologues: Orthologues: macaque RBMY (34% identical), rat Rbmy1j (34% identical), mouse Rbmyf9 (32% identical), mouse Rbmyf2 (32% identical), mouse Rbmyf3 (32% identical), mouse Rbmy (32% identical), mouse Rbmyf1 (32% identical), mouse Rbmyf5 (32% identical), mouse Rbmyf6 (32% identical), mouse Rbmyf7 (32% identical), mouse Rbmyf8 (32% identical), mouse Rbmyf4 (17% identical). Paralogues in human: RBMY1A1 (99% identical), RBMY1B (99% identical), RBMY1E (99% identical), RBMY1F (99% identical), RBMY1J (99% identical), RBMX (48% identical), RBMXL1 (46% identical), RBMXL2 (38% identical), RBMXL3 (31% identical), CIRBP (17% identical), MSI1 (14% identical), RBM3 (14% identical), and 24 more.
Diseases named in the same sentence as RBMY1D in open-access papers:
RBMY1D is named in the same sentence as 1 disease in open-access papers, as found by Europe PMC text mining. Sharing a sentence is not in itself a finding about the gene and the disease. The quoted sentences say what the papers report.
seminoma (1 paper, 2025). A radiosensitive malignant germ cell tumor found in the testis (especially undescended), and extragonadal sites (anterior mediastinum and pineal gland). "Additionally, focal deletions targeting the RBMY gene family (RBMY1A1, RBMY1B, RBMY1D)—male germ cell–specific RNA-binding proteins—were significantly enriched in seminomas (26.6% vs. 12.8% in non-seminomas; P = 0.0078)." (PMID 40568177, 2025).